DNASE2 (deoxyribonuclease 2, lysosomal)
Description:
Hydrolyzes DNA under acidic conditions with a preference for double-stranded DNA. Plays a major role in the clearance of nucleic acids generated through apoptosis, hence preventing autoinflammation. Necessary for proper fetal development and for definitive erythropoiesis in fetal liver and bone marrow, where it degrades nuclear DNA expelled from erythroid precursor cells.
Synonyms: DNASE2A; DNL2; AIPCS; DNL
Tractability: Antibody: UniProt predicts a signal peptide or a membrane-spanning region. PROTAC: ubiquitination databases record sites on it; its protein half-life has been measured.
Target class: Enzyme; Hydrolase
Gene: Protein-coding gene on chromosome 19 (12,875,209 to 12,881,595, reverse strand). Ensembl gene ENSG00000105612.
Subcellular location: Lysosome
Pathways (Reactome):
Vesicle-mediated transport: Lysosome Vesicle Biogenesis
Gene Ontology:
Molecular function: deoxyribonuclease II activity; protein binding; DNA endonuclease activity
Biological process: apoptotic cell clearance; apoptotic DNA fragmentation; DNA catabolic process; DNA metabolic process
Cellular component: extracellular exosome; lysosome
Genetic constraint (gnomAD): Loss-of-function variants: 26 observed, 30.18 expected, observed/expected ratio (o/e) 0.86, 90% interval 0.63 to 1.2. The upper end of that interval is the gene's LOEUF score, 1.2, which puts it in group 5 of 6, group 1 being the genes least tolerant of losing a copy. Missense variants: 415 observed, 467.33 expected, observed/expected ratio (o/e) 0.89, 90% interval 0.82 to 0.96. Synonymous variants: 186 observed, 193.48 expected, observed/expected ratio (o/e) 0.96, 90% interval 0.85 to 1.09.
Homologues: Orthologues: chimpanzee DNASE2 (99% identical), macaque DNASE2 (94% identical), pig DNASE2 (74% identical), dog DNASE2 (72% identical), guinea pig DNASE2 (71% identical), rat Dnase2 (70% identical), mouse Dnase2a (70% identical), rabbit DNASE2 (56% identical), tropical clawed frog dnase2 (44% identical), zebrafish dnase2 (40% identical), Caenorhabditis elegans nuc-1 (32% identical), Drosophila melanogaster DNaseII (31% identical), and 2 more. Paralogues in human: DNASE2B (35% identical).
Diseases named in the same sentence as DNASE2 in open-access papers:
DNASE2 is named in the same sentence as 29 diseases in open-access papers, as found by Europe PMC text mining. Sharing a sentence is not in itself a finding about the gene and the disease. The quoted sentences say what the papers report.
anemia (6 papers, 2017 to 2023). A reduction in the number of red blood cells, the amount of hemoglobin, and/or the volume of packed red blood cells. "Loss-of-function mutations in the DNASE2 gene cause type I interferonopathy characterized by anemia, thrombocytopenia, hepatosplenomegaly, glomerulonephritis, and liver fibrosis." (PMID 35812450, 2022). "Mice deficient in DNASE2 die in-utero, due to an overwhelming IFNα response and lethal anemia." (PMID 31354738, 2019). "The absence of DNase2 in mice causes accumulation of apoptotic cell derived DNA in the lysosomes of liver and bone marrow macrophages causing lethal anemia and cell death." (PMID 31354738, 2019). "DNase2 knockout mice die in late embryogenesis or immediately after birth due to a severe anemia." (PMID 29259162, 2017).
polyarthritis (5 papers, 2009 to 2025). "Altogether, these results indicated that AIM2 is required for the development of polyarthritis in the context of DNase2-deficiency." (PMID 26114879, 2015). "In fact, IL-18-/- mice still develop polyarthritis and express pro-inflammatory cytokines in the context of Dnase2-deficiency." (PMID 26114879, 2015). "Therefore, to elucidate the mechanism of Aim2-deficiency ameliorating DNase2-/--associated polyarthritis, we next assessed systemic signs of inflammation in these mice." (PMID 26114879, 2015). "Note added in proof: While this manuscript was under review, Ellen Gravallese and colleagues have published a likewise approach of studying the role of AIM2 in the context of Dnase2-/- x Ifnar1-/- induced polyarthritis." (PMID 26114879, 2015). "Deficiency of DNAse-1 (DNASE1), a cytoplasmic endonuclease degrading dsDNA, and lysosomal DNAse-2 (DNASE2) deficiency were reported in early-onset SLE patients who may exhibit “atypical” clinical features, such as neonatal pancytopenia, polyarthritis and cholestasis [57▪▪,58]." (PMID 39660463, 2025). "For example, Dnase2-/- mice develop a polyarthritis and induce high levels of TNF-α and IL-6 in affected joints, and blockade of TNF-α or IL-6 has a therapeutic effect on arthritis in Dnase2-/- mice." (PMID 39478149, 2024). "However, given the fact that IL-18 deficiency does not protect Dnase2-deficient animals from polyarthritis or pro-inflammatory gene expression, Aim2-dependent IL-18 production or maturation appears to be an epiphenomenon rather than a cause in this disease model." (PMID 26114879, 2015).
Arthritis (3 papers, 2015 to 2024). Inflammation of a joint. "As such, Dnase2-deficient mice being wild type for Aim2 displayed a significant mean arthritis score of 1.8 compared to Dnase2-competent mice." (PMID 26114879, 2015). "Altogether our data show that AIM2 plays an important role in the recognition of endogenous DNA species in the context of Dnase2-/- associated arthritis, thereby establishing AIM2 as a DAMP sensing PRR." (PMID 26114879, 2015). "With increasing age, signs of chronic polyarthritis progressed to a score of up to 3.4 in the Aim2+/+x Dnase2-/- cohort at 15 months, whereas Aim2-/-x Dnase2-/- mice showed greatly reduced signs of arthritis (mean score of 0.5)." (PMID 26114879, 2015). "In the additional absence of Aim2, Dnase2-deficient mice (Aim2-/-x Dnase2-/-) showed a significant reduction in their signs of arthritis with a clinical score that was comparable to Dnase2-competent mice." (PMID 26114879, 2015).
Alzheimer disease (2 papers, 2024 to 2025). A progressive, neurodegenerative disease characterized by loss of function and death of nerve cells in several areas of the brain leading to loss of cognitive function such as memory and language. "Conversely, high expression of DNASE2 was significantly associated with the structure and function of mitochondria and ribosomes, as well as Alzheimer’s disease." (PMID 40282270, 2025). "In addition, DNase, a commonly used NETs inhibitor, has been successfully applied in the treatment of Alzheimer’s disease, and genetic variants in DNase genes including DNASE1, DNASE2 and DNASE1L3 can result in the downregulation of DNase expression in Alzheimer’s disease." (PMID 38188146, 2024).
Obesity (2 papers, 2018 to 2022). Accumulation of substantial excess body fat. "Downregulation of DNase2 and TREX1 is also observed in HSCs in the obesity-associated liver tumor microenvironment in vivo, and the blockade of this pathway prevented SASP in HSCs and obesity-associated hepatocellular carcinoma development in mice." (PMID 35365245, 2022). "Using this obesity mouse model, we found that the expression levels of both DNase2 and TREX1 in HSCs (which express Desmin) were substantially reduced in obese mice fed a high-fat diet (HFD), as compared to those in lean mice fed a normal diet (ND)." (PMID 29593264, 2018).
autoinflammatory syndrome (1 paper, 2017). A group of disorders of the innate immune system characterized by attacks of seemingly unprovoked inflammation without significant levels of either autoantibodies or autoreactive T cells more characteristic of autoimmune disease. "We describe here a multisystem autoinflammatory syndrome due to biallelic hypomorphic mutations in DNASE2, the gene encoding the 360 amino acid lysosomal DNase DNase II29." (PMID 29259162, 2017).
breast carcinoma (1 paper, 2025). "Through Mendelian randomization analysis, 12 key genes were found to be causally linked to breast cancer pathogenesis, including DNASE2 and ATOH8, which were further validated in external datasets." (PMID 40282270, 2025). "Functional experiments revealed that ATOH8 suppresses breast cancer cell proliferation, migration, and invasion, while DNASE2 promotes these processes." (PMID 40282270, 2025). "Drug sensitivity analysis indicated significant correlations between several commonly used clinical drugs for breast cancer treatment and DNASE2/ATOH8 expression." (PMID 40282270, 2025). "In summary, our findings revealed that DNASE2 significantly promoted the migration and invasion of breast cancer cells, whereas ATOH8 dramatically inhibited proliferation, migration, and invasion." (PMID 40282270, 2025). "Notably, several commonly used clinical drugs for breast cancer management, such as 5-Fluorouracil, exhibited dramatically increased sensitivity to DNASE2 and ATOH8 expression." (PMID 40282270, 2025). "Our study suggests that DNASE2 may promote tumor cell growth and could potentially play a role in enhancing the invasive and migratory behaviors of breast cancer cells, highlighting its potential involvement in the progression of breast cancer." (PMID 40282270, 2025). "In addition, the contrasting effects of ATOH8 and DNASE2 on cell proliferation and migration further underscore their potential as therapeutic targets in breast cancer." (PMID 40282270, 2025). "ATOH8’s inhibitory effect on cell migration and invasion contrasts with DNASE2’s promotion of these cellular processes, suggesting that their distinct roles could be leveraged in developing targeted therapies to modulate breast cancer progression." (PMID 40282270, 2025). "Given the challenges associated with experimental studies on TTC23, we deemed it necessary to further elucidate the biological functions of DNASE2 and ATOH8 in the context of breast cancer." (PMID 40282270, 2025). "The results demonstrated that the expression levels of OLR1, ADIPOR1, CEACAM6, DNASE2, CD53, BMF, and CAMP were significantly elevated in breast cancer samples compared to healthy controls (p < 0.05)." (PMID 40282270, 2025). "The functional assays proved the contribution of DNASE2 and ATOH8 in the progression of breast cancer by modulating the proliferation, migration, and invasion of cancer cells." (PMID 40282270, 2025). "Except for ATOH8, DNASE2, and TTC23, the involvement of the other nine co-expressed genes has been reported in breast cancer." (PMID 40282270, 2025). "Functional studies were conducted to assess the phenotypic effects of siRNA-mediated knockdown of DNASE2 and ATOH8 with siRNA in the breast cancer cell lines MCF-7 and MDA-MB-231." (PMID 40282270, 2025). "Strikingly, functional assays of the less-reported genes DNASE2 and ATOH8 demonstrated their involvement in breast cancer pathogenesis through modulating proliferation, migration, and invasion of cancer cells." (PMID 40282270, 2025). "Functional assays on DNASE2 and ATOH8 revealed their opposing roles in breast cancer cell behavior, consistent with MR analysis predictions." (PMID 40282270, 2025). "Scratch assays demonstrated silencing ATOH8 obviously facilitated wound healing, while knockdown DNASE2 had the opposite effect, implicating the promotive and inhibitory roles of DNASE2 and ATOH8 in the migration of breast cancer cells, respectively." (PMID 40282270, 2025). "Given the challenges associated with experimental studies on TTC23, we have decided to further investigate the biological functions of two genes, ATOH8 and DNASE2, which have not been extensively studied in breast cancer." (PMID 40282270, 2025). "Considering the lack of research on the genes DNASE2 and ATOH8 in the context of breast cancer, we deemed it necessary to further elucidate their functions in breast cancer progression." (PMID 40282270, 2025).
chronic granulomatous disease (1 paper, 2022). Chronic granulomatous disease (CGD) is a rare primary immunodeficiency, mainly affecting phagocytes, which is characterized by an increased susceptibility to severe and recurrent bacterial and fungal infections, along with the development of granulomas. "Genetic defects in PNP, PIK3CD, STAT1, ISG15, IL2RB, GS3, DNASE2 and genes associating chronic granulomatous disease were found among 7 of the 25 patients who underwent genetical testing." (PMID 35964089, 2022).
gastric cancer (1 paper, 2025). A primary or metastatic malignant neoplasm involving the stomach. "In contrast, CDH2 was downregulated in gastric cancer, while EPB41L3, DNASE2, and XPC showed no significant expression differences between gastric cancer and normal tissues." (PMID 40393971, 2025).
liver cancer (1 paper, 2025). An epithelial or non-epithelial malignant neoplasm that arises from the liver. "In liver cancer research, evidence suggested that the knockdown of DNASE2 suppressed proliferation and promoted apoptosis of liver cancer cells, indicating the inhibitory function of DNASE2 in the development of liver cancer." (PMID 40282270, 2025).
ovarian carcinoma (1 paper, 2013). A malignant neoplasm originating from the surface ovarian epithelium. "The anti-EGFRvIII and anti-EGFR antibody guided vectors delivered the DNA constructs for DNase1, DNase1L3, DNase2, DFFB into the nuclei of the human EGFRvIII and EGFR over-expressing ovarian cancer cells from ascites and cultures." (PMID 24587967, 2013).
Splenomegaly (1 paper, 2015). Abnormal increased size of the spleen. "Dnase2-deficient mice developed marked splenomegaly, with spleen sizes being 4–5 fold increased compared to control animals." (PMID 26114879, 2015).
Systemic juvenile idiopathic arthritis (1 paper, 2015). "However, the Dnase2-/- model shares a number of prominent features with Systemic juvenile idiopathic arthritis (sJIA), which can be considered an autoinflammatory disease." (PMID 26114879, 2015).
triple-negative breast carcinoma (1 paper, 2023). An invasive breast carcinoma which is negative for expression of estrogen receptor (ER), progesterone receptor (PR), and human epidermal growth factor receptor 2 (HER2). "We found that the expression of genes related to apoptosis and DNA degradation, such as Cad, PDCD5, Dnase2 and Bax, increased after nsPEF ablation of triple-negative breast cancer in mice." (PMID 37046739, 2023).
tumor (4 papers, 2015 to 2025). "Tumor-derived DNA, such as DNA from dying tumor cells, can activate the cGAS pathway, which implies that DNASE2 may be involved in this process." (PMID 40282270, 2025). "Finally, we conducted external validation using The Cancer Genome Atlas (TCGA) database and further performed functional assays and drug sensitivity analyses on ATOH8 and DNASE2, additional tumor-specific markers identified by MR analysis." (PMID 40282270, 2025). "For the enhancer in chromosome 19, the target genes are TRMT1, TNPO2, NFIX, DNASE2, PRDX2, NANOS3, and LYL1, which was detected in 22 unique tumor samples." (PMID 29207666, 2017).
infection (2 papers, 2018 to 2020). The state of being infected such as from the introduction of a foreign agent such as serum, vaccine, antigenic substance or organism. "Some of these genes are controlled by Dnase2, Ikbkg, Il17a, Snca, Stat2, Tlr3 and their induction is associated with suppression of infection." (PMID 32793510, 2020).
renal disorders (1 paper, 2019). "Remarkably, all the patients with DNASE2 mutations had high titers of anti-DNA Abs and renal disorders." (PMID 31354738, 2019).
DNASE2 also shares sentences with these, for which no sentence is quoted: cancer (4 papers); rheumatoid arthritis (2); Aicardi-Goutières Syndrome (1); autoimmune disease (1); bladder cancer (1); brain tumor (1); cholestasis (1); emphysema (1); glioma (1); Pancytopenia (1); systemic lupus erythematosus (1); tauopathies (1).